IL6 (interleukin 6)
Diseases named in the same sentence as IL6 in open-access papers (continued):
Sharing a sentence is not in itself a finding about the gene and the disease.
depression (continued). "The first study was published twenty years ago, and it has been reported recently that patients suffering from depressive disorder are characterized by increased concentrations of IL-1β, IL-6, and TNF-α compared to controls." (PMID 37834806, 2023). "In diabetes, the development of depressive disorder is related to hyperglycemia and an increase in the circulating pro-inflammatory cytokines IL-1β, IL-6, and TNF-α, known as low-grade inflammation." (PMID 37892186, 2023). "IL-1β, along with IL-6 and TNF, has been linked to sickness behavior and implicated in depressive disorders." (PMID 37762207, 2023). "The treatment options in cancer can also affect the development and manifestations of depressive disorder, for example, when interfering with IL-2, IL-6, IFN-α or steroids which are well-known depression inducers." (PMID 36787313, 2023). "A prospective study with a follow-up period of 12 years also suggested a predictive role of proinflammatory cytokines including C-reactive protein (CRP) and IL-6, in depression." (PMID 36093196, 2022). "IL-6 and IL-1β levels have been reported to be positively correlated with depression scores in postpartum women." (PMID 35721155, 2022). "Salvianolic acid B relieves cerebral injury by reducing IL-6 expression Leonurine, baicalin, geniposide and ferulic acid reduce IL-6 expression to treat depression." (PMID 35833035, 2022). "Additionally, it has been demonstrated that IL-6 levels are associated with presence of internalization and externalization behaviors in children’s, and that increase levels of the IL-6 in childhood are associated with an augmented risk of developing psychosis and depression in young adulthood." (PMID 36225733, 2022). "Exposure to immobilization stress (IS) or social defeat induces depression with neuroinflammation through the upregulated expression of interleukin (IL)-6 and tumor necrosis factor (TNF)-α in mice, resulting in gut inflammation and dysbiosis." (PMID 35631220, 2022). "Cytokines IL-6, IL-1, and TNF-α, known mediators involved in the progression of RA, are strongly associated with stress-related disorders including depression and anxiety." (PMID 35990558, 2022). "In a study of primarily minority women, depressed women (defined by having a score on the Beck Depression Inventory >9) had higher concentrations of IL-6 in the third trimester of pregnancy and showed an increase in IL-6 concentrations across pregnancy." (PMID 35836664, 2022). "For instance, a recent cumulative meta-analysis reported that interleukin-6 (IL-6), IL-1β and C-reactive protein (CRP) are associated with depression." (PMID 35496273, 2022). "Depression-like behaviors are related to increased peripheral blood levels of IL-1β, IL-6, TNF, and CRP, the most reliable biomarkers of inflammation." (PMID 36278007, 2022). "Pre-clinical studies focusing on different chronic pain models with comorbid depression also reported upregulation of IL-1β, IL-6 and TNF-α." (PMID 35733107, 2022). "The biomarkers assessed in the studies involving depression include IL-6 (n = 5), IL-10 (n = 4), TNF-α (n = 4), IL-1β (n = 2), CRP (n = 2), and IL-7 (n = 1)." (PMID 35053845, 2022). "M1 macrophages preferentially produce many of the pro-inflammatory immune cytokines seen in depression, such as IL-6 and TNF-α, as well as pro-inflammatory nitric oxide (NO) and reactive oxygen species." (PMID 35977923, 2022). "The null-findings from the present study for IL-6, TRANCE, and TWEAK are in line with previous findings showing that inflammatory markers are more strongly prospectively associated with clinical depression than with depressive symptoms." (PMID 35360574, 2022). "Acute and chronic stress, anxiety, and depression affect innate and acquired immune responses, including an increase in the level of circulating proinflammatory cytokines, in particular interleukin IL-6." (PMID 35054853, 2022).
depression (continued). "Mechanistically, it is accepted that both depression and sickness behavior are mediated through the actions of interleukin 1 (IL‐1), interleukin 6 (IL‐6), and tumor necrosis factor α (TNFα)." (PMID 35924463, 2022). "In another study, lower levels of HDL-C were reported to be partly a result of low-grade inflammation, which was mediated by IL-6 and has been found in depression." (PMID 35935403, 2022). "Hyperactivation of the hypothalamic–pituitary–adrenal (HPA) axis and continuous increase in glucocorticoid levels in patients with depression inhibited the immune response and increased the serum levels of proinflammatory cytokines IL-6 and IL-2." (PMID 36506019, 2022). "BBB permeability will permit cytokines like IL-6 to enter the brain giving rise to depression-like behaviours." (PMID 35805406, 2022). "In line with this, in a longitudinal Australian cohort (N = 1,692; 55–85 years), the inflammatory markers interleukin-6 (IL-6) and CRP explained 10.9 and 8.1% of the risk of incident CVD hospitalizations associated with depression, respectively." (PMID 36311535, 2022). "Some systematic reviews and meta-analyses have shown that only IL-6 expression is significantly higher in depression." (PMID 36016572, 2022). "Basically, the results confirm the elevated levels of IL-1 and Il-6 as well as cognition impairment among patients with depression." (PMID 35160143, 2022). "We observed elevated IL-1β, IL-6 and reduced IL-10 in the reserpine-induced hyperalgesia and depression comorbidity model group in our present study." (PMID 35733107, 2022). "Recent meta-analyses have revealed high concentrations of IL-6, TNF-α and CRP in depressed patients as compared with healthy controls, but only TNF-α demonstrated a genetic association with major depressive disorders (MDD) among pro-inflammatory cytokines." (PMID 36615742, 2022). "In a cross-sectional study, individuals with depression had higher levels of IL-6 than healthy participants and frequently exhibited altered peripheral inflammatory profiles." (PMID 36685498, 2022). "Studies have shown that depression is related to the expression of a variety of molecules, including IL-6, IL-2, IL-1β, TNF-α, and C-reactive protein (CRP)." (PMID 36010610, 2022). "Two major signaling pathways of IL6, classical signaling (anti-inflammatory) and trans-signaling (pro-inflammatory), were assumed to be related to depression development." (PMID 36009493, 2022). "Several inflammatory markers, namely interleukin-1β (IL-1β), IL-6, and C-reactive protein (CRP), are associated with depression." (PMID 36188478, 2022). "In the current study, we enrolled 217 NSCLC survivors to evaluate levels of TNF‐α, IL‐1β, IL‐6, and IL‐17 and their correlations with anxiety and depression." (PMID 34697903, 2022). "Circulating TNF-α and IL-6 is associated with IBS symptoms of abdominal pain and discomfort, and TNF-α is associated with anxiety, depression, and fatigue in IBS." (PMID 35721806, 2022). "A preponderance of studies has established a positive association between proinflammatory cytokines (including C-Reactive Protein (CRP), Interleukin-1 (IL-1), and Interleukin-6 (IL-6)) and depression, of which apathy is an important component." (PMID 35742625, 2022). "In a clinical trial, subcutaneous injection of tocilizumab, an IL-6 antagonist, significantly decreased depression and anxiety levels in patients with rheumatoid arthritis." (PMID 34979499, 2022). "For example, several research papers reported increased IL-6 levels in patients with major depression, bipolar disorder and schizophrenia." (PMID 36148246, 2022). "The most frequently analyzed peripheral markers of inflammation in the context of depression seem to be IL-1 and IL-6, although there are many others (pro- and anti-inflammatory) also being investigation." (PMID 35160143, 2022).
depression (continued). "Initially, basic immune factors such as C-reactive protein (CRP), interleukin 1 (IL-1) and interleukin 6 (IL-6) were found to be elevated in depression." (PMID 35757204, 2022). "Patients suffering from depression often display increased levels of pro-inflammatory cytokines, such as interleukin-1 (IL-1), interleukin-6 (IL-6) and tumor necrosis factor-α (TNF-α), as well as endogenous metabolites including nesfatin-1 and corticosterone." (PMID 36183107, 2022). "NLRP3, caspase-1, ASC, IL-6, and IL-1β in this signaling pathway are closely related to inflammation and depression." (PMID 36556951, 2022). "Western blot was adopted to detect the effect of Sodium valproate on the protein expressions of interleukin (IL) −1β and IL-6 in hippocampal inflammatory factors of rats with depression." (PMID 35148670, 2022). "Even an experimental study reported resistance to stress-induced depression behavior in IL-6 knockout mice." (PMID 36368945, 2022). "The serum levels of pro-inflammatory cytokines, including interleukin-6 (IL-6), were higher in depressed patients with schizophrenia, bipolar disorder, and major depressive disorder." (PMID 36034871, 2022). "In fact, a growing body of evidence proposes that IL-6 has a central role in the pathogenesis of depression." (PMID 36225733, 2022). "Equally, people with depression have increased plasma IL-6, indicating a probable bidirectional relationship." (PMID 35267893, 2022). "Other studies have shown an association between QoL indicators, including fatigue, anxiety, and depression levels, and increased production of proinflammatory cytokines, including IL-6 and TNF-α." (PMID 34815548, 2022). "Concerning IL-6, baseline peripheral levels of this cytokine also allowed predicting cognitive symptoms of depression at 12 years follow-up, suggesting that IL-6 can precede depression, at least with regard to its cognitive symptoms." (PMID 36187407, 2022). "A link between elevated blood IL-6 levels and depression is well established in both patients and rodent models with IL-6−/− mice being resistant to induced depression-like behaviour." (PMID 34888704, 2022). "Another longitudinal study found that more severe depression at baseline predicted higher levels of IL-6 at follow-up." (PMID 36685498, 2022). "We hypothesized that genetically predicted increased IL-6 and IL-6R activity would be associated with reduced gray matter volume and cortical thickness (CT) in areas highly relevant to neuropsychiatric disorders, including schizophrenia, autism spectrum disorder, and depression." (PMID 35353173, 2022). "Second, important inflammatory mediators such as interferon gamma and IL-6, which induce increasing gut permeability termed “leaky gut,” are significantly increased in patients with depression." (PMID 36275822, 2022). "As such, in recent years, vitamins and constituents of anti-inflammatory pathways, such as IL-1β, IL-6, and IL-18, have been identified as promising pathways to reduce anxiety and depression." (PMID 35277015, 2022). "The released cytokines such as interleukin (IL)-6, IL-1Ɓ, and tumour necrosis factor alpha develop depression by changing the metabolism of the neurotransmitters." (PMID 35945535, 2022). "Given that cytokines, like IL6, are important regulators of HN, it is possible that increased neuronal differentiation (as a potential consequence of altered neuronal apoptosis) may be associated with immune system dysfunction in chronic instances of late-life depression." (PMID 35794184, 2022). "As a typical stress marker, IL-6 was reported to be elevated more prominently in the acute phase of depression or SZ before remission." (PMID 35337097, 2022). "Patients with depression have increased pro-inflammatory cytokines in the blood, such as interleukin-6 (IL-6), interleukin-1β (IL-1β), tumor necrosis factor-α (TNF-α) and other acute-phase proteins and C-reactive protein (CRP)." (PMID 36357867, 2022).
depression (continued). "In a multivariate analysis study on RA severity, elevated serum IL-6 and CRP levels were associated with depression severity." (PMID 35330475, 2022). "There is interest in the role of peripheral interleukin-6 (IL-6) in depression and the effect of treatment (e." (PMID 35633813, 2022). "Clinical depression has been shown to be accompanied with an increase in the pro-inflammatory cytokine, interleukin, such as IL-1b and IL-6." (PMID 36140263, 2022). "Longitudinal studies have also demonstrated that higher levels of serum IL-6 and CRP in childhood are associated with increased risk of psychotic disorders and depression in early-adulthood, consistent with MR studies." (PMID 36277463, 2022). "The prospective cohort study assessed serum CRP, IL-6, and cognitive symptoms of depression over a long period of time, averaging 11.8 years." (PMID 35163141, 2022). "Changes in the serum levels of IL-6 and TNF-α are associated with depression-like behavior both in human and in mice model." (PMID 34115263, 2022). "Although baseline data indicated that IL6 and IL12 were uniquely linked to depression in both males and females, Wave 2 data only confirmed the significant link between IL6 and depression in females." (PMID 35895279, 2022). "Inflammatory signals are thought to play an important role in the development of depression and anxiety disorder, e.g., the cytokines IL-1β, IL-6, and TNFα." (PMID 35456304, 2022). "Our findings also suggest the possibility that elevated IL-6 levels are more relevant for the pathogenesis of psychosomatic syndromes than for depression in patients with HF." (PMID 35271674, 2022). "One study found that the levels of proinflammatory cytokines TNF-α and IL-6 in patients with major depression increased significantly." (PMID 36364213, 2022). "Increased levels of tumor necrosis factor-alpha (TNF-α) and interleukin-6 (IL-6) in cerebrospinal fluid and brain parenchyma were detected in patients with depression." (PMID 35036964, 2022). "Previous studies with major depressive disorder, schizophrenia, and generalized anxiety disorder showed that higher levels of IL-1β, IL-2, IL-6, and CCL2 were related to the severity of psychiatric symptoms." (PMID 35504954, 2022). "One study found that concentrations of IL-6 at approximately 15 weeks gestation were positively correlated with depressive symptoms (as measured by the Center for Epidemiologic Studies Depression Scale or CES-D) after controlling for BMI." (PMID 35836664, 2022). "We performed ROC analysis to distinguish the depression of patients with different clinical characteristics according to the IL-6, TNF-α, and CRP values." (PMID 35757220, 2022). "First, in addition to RA-like symptoms, CIA mice exhibited depression-like behaviors, elevated blood levels of IL-6, downregulation of synaptic proteins (e.g., PSD-95 and GluA1) in the PFC, and abnormal composition of gut microbiota." (PMID 35650202, 2022). "IL-6, one of the proinflammatory cytokines, is a signaling promoter and pathological product of depression." (PMID 36364213, 2022). "Further, elevated levels of TNF-α, IL-6 (episode of depression), and IL-23 (episode of mania) were reported in BD." (PMID 34791253, 2022). "It is similar to the results found in this study that the levels of IL-1β and IL-6 protein in the hippocampus of rats with depression increased." (PMID 35148670, 2022). "In several models of depression, the expressions of inflammatory cytokines such as Tnfα, Il1b, and Il6 in the hippocampus were increased and higher microglial activation in the hippocampus was observed compared with controls." (PMID 36151082, 2022). "Studies have shown that high levels of IL-6 are related to the chronic course of depression, and the severity of depression in patients with high expression of IL-6 is increased as well." (PMID 36364213, 2022).
depression (continued). "IL-6 and IL-8 reflecting low grade inflammation are the most relevant cytokines, since activation of the innate immune system in depression pathophysiology seems to be one of the most promising theories." (PMID 35022028, 2022). "The current study also revealed that serum TNF‐α, IL‐1β, IL‐6, and IL‐17 were positively correlated with anxiety and depression risks in NSCLC survivors." (PMID 34697903, 2022). "People with depression are characterized by increased levels of pro-inflammatory markers, such as interleukin (IL) IL-6, IL-1, tumor necrosis factor alpha (TNF-α) and C-reactive protein (CRP)." (PMID 36554751, 2022). "Previous studies of e.g. CSF IL-6 in depression have included far smaller sample sizes compared to this present study and the large sample size of this study is an important strength." (PMID 35022028, 2022). "Conversely, while ART normalises the levels of some inflammatory cytokines in people living with HIV, concentrations of other cytokines such as IL-6 and CRP (which are strongly linked to depression) remain elevated." (PMID 35618889, 2022). "A wide array of previous studies have presented the inflammatory effect of adipose tissue in patients with depression, and adipose tissue has also been reported to function as a major source of commonly known pro-inflammatory biomarkers such as IL-6." (PMID 35232419, 2022). "High IL-1β (P=0.011, adjusted P=0.044), IL-6 (P=0.010, adjusted P=0.040), and IL-17 (P=0.011, P=0.044 after adjustment), but not TNF-α (P=0.104, P=0.416 after adjustment), were associated with depression occurrence." (PMID 35239774, 2022). "Increased levels of IL-6 and TNF-α have been associated with different brain disorders, such as schizophrenia and major depressive disorder." (PMID 34115263, 2022). "Some records are studies that combined both peripheral markers of inflammation (IL-1 and IL-6) with depression, and some with just one peripheral marker." (PMID 35160143, 2022). "Accumulating evidence suggests that pro-inflammatory cytokines, in particular peripheral IL-6, play an important role in the pathogenesis of depression." (PMID 36547090, 2022). "In breast cancer patients, positive correlations have been observed between depression and inflammatory markers, such as IL-1β, IL-6, and tumor necrosis factor-alpha (TNF-α)." (PMID 36615742, 2022). "A recent meta-analysis investigating immunological differences in blood samples from patients with depression compared to controls have amongst others found interleukin-6 (IL-6) and IL-8 to be elevated in patients with depression." (PMID 35022028, 2022). "Growing studies have shown that increased levels of kynurenine, quinolinic acid, and IL-6 have all been found in patients with depression." (PMID 35054853, 2022). "A meta-analysis indicated a significant increase in pro-inflammatory cytokines, such as tumor necrosis factor (TNF)-α and interleukin-6 (IL-6), in patients with depression." (PMID 35252227, 2022). "The heightened concentration of the pro-inflammatory cytokine IL-6 in the Severe class is consistent with it being a biomarker of depression." (PMID 35784438, 2022). "Faecalibacterium prausnitzii administration increases the IL-10 level and reduces IL-6 as well as CORT levels in depression-like and anxiety-like rats." (PMID 35744601, 2022). "Higher levels of Il-6, CRP, and dysregulation of the cortisol response are linked with cardiovascular disease and depression." (PMID 35279110, 2022). "Studies have found that individuals with major depressive disorder have elevated levels of IL‐1 and IL‐6 in blood and cerebrospinal fluid (CSF) and C‐reactive protein in serum." (PMID 36239436, 2022). "In RCTs for patients with major depression or anxiety disorder, MBIs significantly reduced inflammatory cytokines including IL-6, suggesting the potential use of MBIs to improve depression- or anxiety-related low-grade inflammation." (PMID 35682203, 2022).